EGFR (epidermal growth factor receptor)
Diseases named in the same sentence as EGFR in open-access papers (continued):
Sharing a sentence is not in itself a finding about the gene and the disease.
lung adenocarcinoma (continued). "To determine if DOK2 genomic loss was a feature of a specific genomic class of lung adenocarcinoma, we analyzed the relationship of DOK2 loss with mutation of EGFR or KRAS in 199 primary human lung adenocarcinomas." (PMID 24255704, 2013). "On the other hand, the presence of a mutated EGFR receptor was found to be associated with a favorable response to certain types of EGFR inhibitors, namely, gefitinib and erlotinib in patients with lung adenocarcinoma." (PMID 23841084, 2013). "Significant differences were observed in the EGFR mutations between Uighur lung adenocarcinoma patients and Han lung adenocarcinoma patients (P < 0.001)." (PMID 23425899, 2013). "For lung adenocarcinomas, epidermal growth factor receptor (EGFR) tyrosine kinase inhibitors have been approved for treatment of tumors carrying EGFR gene mutations, and crizotinib for tumors with anaplastic lymphoma kinase (ALK) gene rearrangements." (PMID 24236184, 2013). "EGFR mutation is a relatively frequent driver mutation in lung adenocarcinoma and is found in approximately 10% of white patients and in over 40% of East Asian patients." (PMID 23936355, 2013). "This study investigated the staining protocol, staining pattern, scoring methods, and cut off value to determine the diagnostic power of EGFR mutation-specific IHC in Chinese lung adenocarcinoma patients." (PMID 23419122, 2013). "In the present study, we demonstrated PCV and EGFR mutation status as independent prognostic factors in untreated advanced lung adenocarcinoma patients." (PMID 23879483, 2013). "Especially in those with advanced disease stage, miR-195 and miR-122 expression were found to be associated with EGFR mutation and overall survival of lung adenocarcinoma." (PMID 24282590, 2013). "The aim of this study is to investigate the prevalence of EGFR mutations in Uighur lung adenocarcinoma patients by using a rapid and sensitive detection method and to analyze EGFR mutation differences compared with Han lung adenocarcinoma patients." (PMID 23425899, 2013). "EGFR mutations were detected in 11 (16.2%) of the 68 Uighur lung adenocarcinoma patients and in 32 (45.7%) of the 70 Han lung adenocarcinoma patients." (PMID 23425899, 2013). "In the current study we delineate genomic and transcriptional alterations in lung adenocarcinoma stratified by EGFR and KRAS mutation status." (PMID 24205279, 2013). "Eighty ALK-rearranged and 213 ALK-negative (91 epidermal growth factor receptor-mutated; 29 K-ras-mutated; 93 triple-negative) resected lung adenocarcinomas were analyzed for several histomorphological parameters and histological subtype." (PMID 24194854, 2013). "Epidermal growth factor receptor (EGFR) gene mutations localized within the tyrosine-kinase (TK) domain occur in approximately 10–15 % of Caucasians with lung adenocarcinoma." (PMID 23892415, 2013). "Examples include gefitinib for EGFR mutation-positive lung adenocarcinoma and crizotinib for EML4-ALK positive lung adenocarcinoma." (PMID 23617234, 2013). "All patients except one were diagnosed with adenocarcinoma of the lung with EGFR mutation at initial diagnosis." (PMID 24369725, 2013). "On the other hand, loss of DOK2 is also observed in EGFR wild-type tumors, and Dok2 null mice do spontaneously develop lung adenocarcinoma." (PMID 24255704, 2013). "We provide a comprehensive overview of the genomic and transcriptional landscape in lung adenocarcinoma stratified by EGFR and KRAS mutations." (PMID 24205279, 2013). "In a case of lung adenocarcinoma, the expression of an activating EGFR mutation was demonstrated to differ between areas with distinctive histological patterns." (PMID 24280411, 2013). "This contrasts with the situation observed in lung adenocarcinoma where the key mechanism of EGFR activation, underlying sensitivity to EGFR inhibitors, corresponds to activating mutations within the EGFR tyrosine kinase domain." (PMID 23565769, 2013).
lung adenocarcinoma (continued). "There were no significant gender differences in age, pathological nodal status, lymphatic permeation, blood vessel invasion or mutation spectra for either EGFR- or KRAS-mutated lung adenocarcinomas." (PMID 24179496, 2013). "To further validate the effect of JAK2 inhibition on tumor growth in vivo, we performed xenograft assays with HCC-827 lung adenocarcinoma cells, which are driven by an activating mutation (E746-A750 deletion) in EGFR." (PMID 22319590, 2012). "In the investigated Dutch cohort, patients with malignant pleural/pericardial effusion of lung adenocarcinoma have an increased frequency of EGFR mutations." (PMID 22528563, 2012). "Unfortunately, only 20 percent of adenocarcinomas of the lung bear activating mutations of EGFR and are responsive to EGFR-targeted therapy." (PMID 22815959, 2012). "Presence of mERα expression together with EGFR mutation was found to be an independent prognostic factor for survival in patients with lung adenocarcinoma, suggesting cross-talk between mERα and EGFR mutation." (PMID 22784503, 2012). "In 2004, it was discovered that the reason why some patients with adenocarcinomas of the lung responded in spectacular form to treatment with tyrosine kinase inhibitors (TKIs) of EGFR was specifically due to the existence of activating mutations of this gene." (PMID 22952784, 2012). "The overall frequency of EGFR mutations in lung adenocarcinomas in this West European population is within the frequency range of North American and South European populations, whereas KRAS mutation frequency is higher than in any population described to date." (PMID 22528563, 2012). "Until today, several biological events have been identified in lung adenocarcinoma, including epidermal growth factor receptor (EGFR) mutations and anaplastic lymphoma kinase (ALK) translocations, offering new hopes to patients with metastatic disease." (PMID 27398239, 2012). "By contrast, evaluation of EGFR mutations as predictive assay for tyrosine kinase inhibitors in advanced adenocarcinoma of the lung was considered a major breakthrough, and emerged as a new diagnostic tool." (PMID 22848476, 2012). "In the present study, we found that patients with lung adenocarcinoma who had both mERα expression and EGFR mutation showed significantly poorer outcomes." (PMID 22784503, 2012). "Based on these data from previous studies, we investigated the association between the expression of mERα and EGFR mutation in lung adenocarcinoma." (PMID 22784503, 2012). "This study demonstrated that the presence of mERα expression together with EGFR mutation is an independent prognostic factor in patients with lung adenocarcinoma, suggesting the existence of cross-talk between mERα expression and EGFR mutation." (PMID 22784503, 2012). "They examined 60 lung adenocarcinomas defined as sensitive or refractory to gefitinib or erlotinib for mutations in EGFR and KRAS." (PMID 23691449, 2012). "KRAS mutations are reported in 15–25% of patients with lung adenocarcinoma and are typically mutually exclusive with EGFR mutations or ALK gene rearrangements." (PMID 25562798, 2012). "Study of the mutational state of EGFR became a matter of urgent necessity in patients with adenocarcinomas of the lung." (PMID 22952784, 2012). "The second model corresponded to PC-9 cell line, a human lung adenocarcinoma driven by the oncogenic activation of the EGFR pathway caused by a deletion (Del E746–A750) in the exon 19 of the EGFR." (PMID 22590613, 2012). "Strong nuclear expression of ERß has been shown to be correlated with the presence of EGFR mutation, and the favorable prognostic significance of ERß expression has been shown to be influenced by the presence of EGFR mutation in lung adenocarcinoma." (PMID 22784503, 2012). "Several investigations have also revealed that patients with lung adenocarcinoma in Asia (30%–50%) show a higher frequency of EGFR mutations than those in the United States (10%)." (PMID 24212826, 2011).
lung adenocarcinoma (continued). "The epidermal growth factor receptor (EGFR) has recently been scrutinised as a potential target in lung adenocarcinoma therapy because of its overexpression in and association with poor prognosis of many solid tumours." (PMID 21285982, 2011). "Objetives of this study were: 1) To analyze the EGFR gene mutations in a population diagnosed with lung adenocarcinoma from Northern Spain." (PMID 21575252, 2011). "In contrast to lung adenocarcinomas in which activating EGFR mutations result in ligand-independent signaling, such activating EGFR mutations are infrequent in HNSCC." (PMID 21776391, 2011). "Examples include the use of epidermal growth factor receptor (EGFR) inhibitors such as gefitinib and erlotinib for lung adenocarcinomas bearing EGFR mutations, and of ALK inhibitors such as crizotinib for lung adenocarcinomas bearing EML4-ALK translocations." (PMID 21666749, 2011). "Lung adenocarcinoma has the highest possibility (10%–40%) of harboring somatic mutations in the ATP-binding kinase domain of EGFR." (PMID 24212826, 2011). "LOH events at 9q and 16p, key features of lung cancer, have been reported to occur at similar frequencies in AAH and adenocarcinoma, and the mutually exclusive natures of KRAS and EGFR mutations reported in lung adenocarcinoma are maintained in AAH lesions." (PMID 21731750, 2011). "A similar association between gefitinib resistance and HGF induced c-MET activation has also been reported for lung adenocarcinomas containing activating EGFR mutations." (PMID 21283737, 2011). "the aim of this study was to identify the discriminating capacity of IHC scoring for the detection of the two specific EGFR mutations, L858R and E746-A750 deletion, in patients with adenocarcinoma of the lung." (PMID 21858063, 2011). "Two classes of mutation account for approximately 90% of EGFR mutations reported to date in lung adenocarcinoma." (PMID 21575212, 2011). "Major recurrent mutations in lung adenocarcinoma have been found to occur in EGFR, KRAS, HER2, BRAF, ALK and ROS1." (PMID 22140546, 2011). "Loss of EGFR mutations in metastatic lung adenocarcinomas compared to primary tumours has also been reported." (PMID 21949883, 2011). "Mutations in the kinase domain of the epidermal growth factor receptor result in STAT3 activation via the IL-6–JAK pathway in human lung adenocarcinoma." (PMID 21730976, 2011). "It is also known that EGFR mutations or amplifications play a role in lung adenocarcinomas, uveal melanomas, and possibly in high-grade gliomas, although the role EGFR plays with respect to clinical behavior of the tumor has been controversial." (PMID 21714919, 2011). "We aimed to identify the discriminating capacity of immunohistochemical (IHC) scoring to detect L858R and E746-A750 deletion mutation in lung adenocarcinoma patients and predict EGFR TKIs response." (PMID 21858063, 2011). "For example, persistently activated STAT3 is found in 50% of lung adenocarcinomas and is primarily observed in tumors harboring mutations in the epidermal growth factor receptor (EGFR)." (PMID 21533169, 2011). "Our results revealed that the deletion in exon 19 and the L858R point mutation were the major EGFR mutations in lung adenocarcinomas, and EGFR mutations were significantly associated with smoking status." (PMID 20637128, 2010). "The presence of EGFR mutations was shown to enhance radiation response; for patients with EGFR mutation and brain metastases from lung adenocarcinoma, WBRT delivered concurrently with EGFR inhibitors produced a response rate of 84%." (PMID 24281220, 2010). "In previous studies, EGFR mutations were reported in about 22% to 67%, 10% to 24%, and 3% to 25% of Asian population, Southern European, and American populations with lung adenocarcinomas." (PMID 20637128, 2010). "EGFR mutations have earlier been identified as one of the key mutations affecting lung adenocarcinoma patients in a comprehensive study of 188 patients." (PMID 20126411, 2010).
lung adenocarcinoma (continued). "This situation contrasts with in lung adenocarcinoma in which the key mechanism of EGFR activation underlying sensitivity to EGFR inhibitors corresponds to activating mutations within the EGFR tyrosine kinase domain." (PMID 21139621, 2010). "Somatic mutations in the EGFR kinase domain are found in a subset of lung adenocarcinomas and are associated with sensitivity to TKI (point mutations G719A/C in exon 18, L858R and L861Q in exon 21 and in-frame deletions at position 745 of exon 19)." (PMID 19174819, 2009). "Given the comparable embryonal tissue origin between lung adenocarcinoma and SGCs and the potential for genotype-directed trials of EGFR inhibitors, we undertook a comprehensive mutational analysis of EGFR in SGCs." (PMID 19174819, 2009). "In a similar way, Braf mutation is also known to cause resistance to anti-EGFR therapy in colorectal cancers and primary lung adenocarcinomas." (PMID 19878607, 2009). "Phosphorylated Stat3/5 appears to be particularly important for survival of human lung adenocarcinoma cells harboring certain EGFR mutations." (PMID 18461184, 2008). "Partial tumour responses have been observed in two patients with adenocarcinoma of the lung, with a complex heterozygous EGFR mutation in one patient." (PMID 18026190, 2008). "Two mutations account for approximately 90% of EGFR mutations reported to date in lung adenocarcinoma." (PMID 18542074, 2008). "Possible candidates to undergo such mutations include a multitude of gene products described in studies of human lung tumors, some of these studies have implicated the EGFR/IL-6/Stat3 pathway in the pathogenesis of lung adenocarcinomas." (PMID 18461184, 2008). "Somatic mutations of EGFR were found in lung adenocarcinoma that lead to exquisite dependency on EGFR signaling; thus patients with EGFR-mutant tumors are at high chance of response to EGFR inhibitors." (PMID 19079597, 2008). "Recent studies have indicated that EGFR mutations are mutually exclusive with KRAS mutations in lung adenocarcinomas." (PMID 18485879, 2008). "Activating mutations within the epidermal growth factor receptor (EGFR) identify lung adenocarcinoma patients with improved clinical responses to tyrosine kinase inhibitors gefitinib and erlotinib." (PMID 18542074, 2008). "Point mutations in the kinase domain of mutant epidermal growth factor receptors (EGFRs) are associated with acquired resistance to the EGFR inhibitors, gefitinib (Iressa) and erlotinib (Tarceva) in human lung adenocarcinoma." (PMID 17726540, 2007). "The mutations within the tyrosine kinase domain of EGFR associated with gefitinib sensitivity were thus found to specifically occur in lung adenocarcinoma patients with a low exposure of tobacco smoking." (PMID 16552419, 2006). "Using the same predictor, we classified human lung adenocarcinomas and captured the majority of tumors with high levels of EGFR activation as well as those harbouring activating mutations in the kinase domain." (PMID 17096850, 2006). "As a positive control for mutation detection, we sequenced EGFR exons 18–21 in 44 adenocarcinoma of the lung and found 2 (5%) with somatic delE746-A750 mutations, previously reported to be associated with gefitinib responsiveness." (PMID 17150109, 2006). "The Smoking effect is therefore very slight for oncogenesis via EGFR mutations of lung adenocarcinoma for the population who had stopped smoking for more than 20 years previously, whereas K-ras mutations were more frequently found in smokers." (PMID 16552419, 2006). "In conclusion, the mutations within the tyrosine kinase domain of EGFR were found to specifically occur in lung adenocarcinoma patients with a low exposure of tobacco smoking." (PMID 16552419, 2006). "Probably, EGFR mutations have a similar significance to K-ras mutations in oncogenesis of lung adenocarcinomas." (PMID 16052218, 2005).
lung adenocarcinoma (continued). "Somatic mutations in the gene for the epidermal growth factor receptor (EGFR) are found in adenocarcinomas of the lung and are associated with sensitivity to the kinase inhibitors gefitinib (Iressa) and erlotinib (Tarceva)." (PMID 15696205, 2005). "First, they extend previous data from our group and others showing that lung adenocarcinomas containing EGFR mutations are associated with sensitivity to gefitinib or erlotinib (17 of 17 in this series; 100% observed response rate; 95% CI, 82%–100%)." (PMID 15696205, 2005). "We systematically evaluated 60 lung adenocarcinomas from patients with known responses to either of these drugs for the presence of mutations in EGFR (exons 18 through 21) and KRAS2 (exon 2)." (PMID 15696205, 2005). "ErbB-2 and EGFR (epidermal growth factor receptor) are expressed in lung adenocarcinomas and associated with a poor prognosis." (PMID 7599067, 1995). "A 68-year-old man with stage IVA lung adenocarcinoma harboring an uncommon EGFR L861Q mutation and a programmed death-ligand 1 (PD-L1) tumor proportion score of <1% received first-line osimertinib (80 mg once daily) for nine months, achieving a partial response before disease progression." (PMID 42158804, 2026). "Here, we report a case of advanced lung adenocarcinoma harboring EGFR exon 21 L858R mutations who finally achieved partial response (PR) in the lung lesion following patient-derived tumor organoid (PDTO)-guided personalized therapy, even after multiple lines of systemic treatment." (PMID 42205749, 2026). "However, in the subset of patients with stage IV lung adenocarcinoma—a population characterized by a high burden of osseous metastasis and distinct molecular features (e.g., > 50% EGFR mutation rate)—clinical response to denosumab is notably heterogeneous." (PMID 41495545, 2026). "No consistent associations between TAP1 or TAP2 downregulation and age, gender, disease stage or smoking status were identified, and the frequency of cancer cell TAP1 and/or TAP2 downregulation was comparable across lung adenocarcinomas harboring activating mutations in EGFR or KRAS." (PMID 40091029, 2025). "This could be due to the inherent biological complexity of lung adenocarcinoma, where the imaging phenotype influenced by EGFR mutation may be subtle and confounded by other genetic and microenvironmental factors." (PMID 41244899, 2025). "Notably, cfDNA analysis enables easy identification of somatic mutations that explain acquired resistance, such as EGFR T790M in lung adenocarcinoma." (PMID 40148708, 2025). "The first evidence derives from a monocentric study that evaluated the potential of parallel serial assessment of somatic mutation and methylation profile in monitoring the response to osimertinib in patients with stage IV lung adenocarcinoma and EGFR T790M mutation." (PMID 41008870, 2025). "The purpose of this pilot study is to investigate whether sPD-L1 could potentially be a predictive biomarker in patients with EGFR-mutated (EGFRmut) lung adenocarcinoma treated with EGFR TKIs based on a comparison of sPD-L1 blood levels and clinical outcomes." (PMID 39852160, 2025). "Under the selective pressure of TKI treatment, lung adenocarcinoma with EGFR mutations caused by these type II alveolar cells may be re-differentiated into SCLC." (PMID 40134592, 2025). "Although furmonertinib is generally well-tolerated and no severe drug-related interstitial lung disease (ILD) has been reported in the literature to date, we present a case of furmonertinib-induced ILD in a 71-year-old woman with EGFR-mutated lung adenocarcinoma (LUAD)." (PMID 41585870, 2025). "In addition, a patient with lung adenocarcinoma concomitant EGFR mutations and EML4-ALK fusion benefited from combination treatment with EGFR-TKIs and ALK-TKIs." (PMID 40052122, 2025).